ATP5MGL (ATP synthase membrane subunit g like)
Description:
Mitochondrial membrane ATP synthase (F(1)F(0) ATP synthase or Complex V) produces ATP from ADP in the presence of a proton gradient across the membrane which is generated by electron transport complexes of the respiratory chain. F-type ATPases consist of two structural domains, F(1) - containing the extramembraneous catalytic core, and F(0) - containing the membrane proton channel, linked together by a central stalk and a peripheral stalk. During catalysis, ATP synthesis in the catalytic domain of F(1) is coupled via a rotary mechanism of the central stalk subunits to proton translocation. Part of the complex F(0) domain. Minor subunit located with subunit a in the membrane (By similarity).
Synonyms: ATP5K2; ATP5L2; dJ222E13.5
Tractability: PROTAC: ubiquitination databases record sites on it.
Gene: Protein-coding gene on chromosome 22 (42,639,803 to 42,640,601, reverse strand). Ensembl gene ENSG00000249222.
Subcellular location: Mitochondrion membrane
Subcellular location (Human Protein Atlas): Mitochondria; Principal piece
Gene Ontology:
Molecular function: proton-transporting ATP synthase activity, rotational mechanism; proton transmembrane transporter activity
Biological process: proton motive force-driven ATP synthesis; proton transmembrane transport
Cellular component: mitochondrion; mitochondrial inner membrane; proton-transporting ATP synthase complex; mitochondrial membrane
Genetic constraint (gnomAD): Loss-of-function variants: 8 observed, 6.91 expected, observed/expected ratio (o/e) 1.16, 90% interval 0.67 to 1.84. That is too few expected variants to judge how well the gene tolerates losing a copy. Missense variants: 119 observed, 119.86 expected, observed/expected ratio (o/e) 0.99, 90% interval 0.86 to 1.16. Synonymous variants: 56 observed, 47.15 expected, observed/expected ratio (o/e) 1.19, 90% interval 0.96 to 1.48.
Homologues: Orthologues: dog ATP5MG (85% identical), pig ATP5MG (80% identical), mouse Atp5mg (74% identical), mouse Atg5lrt (69% identical), rat Atp5mg (66% identical), zebrafish atp5l (61% identical), Drosophila melanogaster ATPsynG (49% identical), Drosophila melanogaster ATPsynGL (38% identical), Caenorhabditis elegans asg-1 (35% identical), Caenorhabditis elegans asg-2 (33% identical). Paralogues in human: ATP5MG (89% identical).